ATP2C1 (ATPase secretory pathway Ca2+ transporting 1)
Description:
ATP-driven pump that supplies the Golgi apparatus with Ca(2+) and Mn(2+) ions, both essential cofactors for processing and trafficking of newly synthesized proteins in the secretory pathway. Within a catalytic cycle, acquires Ca(2+) or Mn(2+) ions on the cytoplasmic side of the membrane and delivers them to the lumenal side. The transfer of ions across the membrane is coupled to ATP hydrolysis and is associated with a transient phosphorylation that shifts the pump conformation from inward-facing to outward-facing state. Plays a primary role in the maintenance of Ca(2+) homeostasis in the trans-Golgi compartment with a functional impact on Golgi and post-Golgi protein sorting as well as a structural impact on cisternae morphology. Responsible for loading the Golgi stores with Ca(2+) ions in keratinocytes, contributing to keratinocyte differentiation and epidermis integrity. Participates in Ca(2+) and Mn(2+) ions uptake into the Golgi store of hippocampal neurons and regulates protein trafficking required for neural polarity (By similarity). May also play a role in the maintenance of Ca(2+) and Mn(2+) homeostasis and signaling in the cytosol while preventing cytotoxicity.
Synonyms: SPCA1; KIAA1347; ATP2C1A; PMR1; BCPM; HHD; hSPCA1
Tractability: Small molecule: a structure with a bound ligand is known; it belongs to a druggable protein family. Antibody: UniProt predicts a signal peptide or a membrane-spanning region; its Gene Ontology location is reachable by antibodies, with medium confidence. PROTAC: ubiquitination databases record sites on it; its protein half-life has been measured.
Gene: Protein-coding gene on chromosome 3 (130,850,511 to 131,016,712, forward strand). Ensembl gene ENSG00000017260.
Subcellular location: Golgi apparatus, trans-Golgi network membrane; Golgi apparatus, Golgi stack membrane
Subcellular location (Human Protein Atlas): Golgi apparatus
Pathways (Reactome):
Transport of small molecules: Ion transport by P-type ATPases
Gene Ontology:
Molecular function: P-type calcium transporter activity; P-type manganese transporter activity; ATP binding; ATP hydrolysis activity; nucleotide binding
Biological process: actin cytoskeleton organization; calcium ion transport; calcium-dependent cell-cell adhesion; epidermis development; Golgi calcium ion homeostasis; Golgi calcium ion transport; intracellular calcium ion homeostasis; positive regulation of canonical NF-kappaB signal transduction; positive regulation of Golgi to plasma membrane protein transport; trans-Golgi network membrane organization; calcium ion transmembrane transport; manganese ion transport; manganese ion transmembrane transport
Cellular component: Golgi apparatus; Golgi membrane; membrane; trans-Golgi network; cis-Golgi network membrane; endoplasmic reticulum; Golgi cisterna membrane; plasma membrane; cytoplasm; endomembrane system
Genetic constraint (gnomAD): Loss-of-function variants: 22 observed, 78.22 expected, observed/expected ratio (o/e) 0.28, 90% interval 0.2 to 0.4. The upper end of that interval is the gene's LOEUF score, 0.4, which puts it in group 1 of 6, group 1 being the genes least tolerant of losing a copy. Missense variants: 579 observed, 887.23 expected, observed/expected ratio (o/e) 0.65, 90% interval 0.61 to 0.7. Synonymous variants: 264 observed, 295.33 expected, observed/expected ratio (o/e) 0.89, 90% interval 0.81 to 0.99.
Homologues: Orthologues: chimpanzee ATP2C1 (99% identical), macaque ATP2C1 (99% identical), rabbit ATP2C1 (99% identical), guinea pig ATP2C1 (99% identical), dog ATP2C1 (98% identical), rat Atp2c1 (97% identical), mouse Atp2c1 (97% identical), pig ATP2C1 (96% identical), tropical clawed frog atp2c1 (88% identical), zebrafish atp2c1 (81% identical), Drosophila melanogaster SPoCk (64% identical), Caenorhabditis elegans pmr-1 (57% identical), and 5 more. Paralogues in human: ATP2C2 (66% identical), ATP2A2 (38% identical), ATP2A3 (37% identical), ATP2A1 (36% identical), ATP2B3 (31% identical), ATP2B1 (30% identical), ATP2B2 (30% identical), ATP1A3 (30% identical), ATP2B4 (30% identical), ATP1A4 (29% identical), ATP1A2 (29% identical), ATP1A1 (29% identical), and 9 more.
Diseases named in the same sentence as ATP2C1 in open-access papers:
ATP2C1 is named in the same sentence as 39 diseases in open-access papers, as found by Europe PMC text mining. Sharing a sentence is not in itself a finding about the gene and the disease. The quoted sentences say what the papers report.
Hailey-Hailey disease (31 papers, 2013 to 2026). Benign chronic familial pemphigus of Hailey-Hailey is characterized by rhagades mostly located in the armpits, inguinal and perineal folds (scrotum, vulva). "Genetic analysis identified a donor splice-site mutation in ATP2C1 (c.899+1G>T), confirming the diagnosis of Hailey-Hailey disease." (PMID 42158788, 2026). "Hailey-Hailey disease, also known as familial benign chronic pemphigus, is a rare autosomal dominant acantholytic dermatosis caused by abnormalities in ATP2C1." (PMID 42158788, 2026). "Hailey-Hailey disease (HHD) is a rare autosomal dominant genodermatosis caused by mutations in the ATP2C1 gene, leading to impaired calcium homeostasis and epidermal acantholysis." (PMID 40718282, 2025). "Hailey-Hailey disease (HHD) is a rare autosomal dominant skin disease caused by mutations in the ATP2C1 gene, which encodes the secretory Ca2+/Mn2+-ATPase (SPCA1) pump in the Golgi apparatus." (PMID 39241028, 2024). "The Golgi-specific Ca2+-ATPase in Hailey-Hailey disease patient ATP2C1 shows multiple point mutations, leading to unbalanced Ca2+ homeostasis." (PMID 39539285, 2024). "Hailey-Hailey disease is an autosomal dominant disorder caused by a mutation in the ATP2C1 gene and characterized by recurrent blisters, erosions, and crust in intertriginous areas." (PMID 39295647, 2024). "Hailey-Hailey disease is a rare hereditary skin disease caused by mutations in the ATP2C1 gene encoding the secretory pathway Ca2+/Mn2+-ATPase 1 (SPCA1) protein." (PMID 38014829, 2023). "Hailey-Hailey disease (OMIM #169600), also called benign chronic pemphigus, is another autosomal dominant skin disorder caused by heterozygous variants in the ATP2C1 gene encoding a Ca2+-ATPase expressed in the membrane of the Golgi apparatus." (PMID 32354065, 2020). "Many independent genetic variants in ATP2A2 and ATP2C1 in human patients with Darier disease or Hailey-Hailey disease have been described." (PMID 32354065, 2020). "The yeast model has provided important information that can explain how in Hailey-Hailey disease loss of ATP2C1 affects human keratinocytes homeostasis." (PMID 31771413, 2019). "PMR-1 function is evolutionary conserved from yeast to human, where mutations in the orthologous gene ATP2C1 cause Hailey-Hailey disease." (PMID 31771413, 2019). "On the other hand, mutations in the human Pmr1 ortholog, ATP2C1/hSPCA, cause Hailey-Hailey disease, a genetic disorder accompanied by skin blisters." (PMID 31201205, 2019). "ATP2C1 is a Ca2+ and Mn2+ pump localized in the Golgi complex and is associated with Hailey-Hailey disease and other disorders." (PMID 28768697, 2017). "ATP2C1 mutations have been identified as having a causative role in Hailey-Hailey disease, an autosomal-dominant skin disorder." (PMID 27528123, 2016). "Identification of three novel and one recurrent mutation in ATP2C1 in Lebanese families with Hailey-Hailey disease." (PMID 25658765, 2015). "Hailey-Hailey disease results in blistering of the epidermis and is caused by a mutation in the ATP2C1 gene, resulting in desmosomal defects." (PMID 25006807, 2014). "Defects in the human SPCA1/ATP2C1 gene cause Hailey-Hailey disease (MIM# 169600), a genodermatosis characterized by cutaneous blisters and fissures as well as keratinocyte cell adhesion defects." (PMID 23696750, 2013). "Mutation of ATP2C1 gene is associated with Hailey-Hailey disease." (PMID 36578782, 2022). "Defects in the human ortholog of PMR1, ATP2C1, are associated with Hailey-Hailey disease." (PMID 32957533, 2020). "In human, mutations on the PMR-1 orthologues ATP2C1 cause Hailey-Hailey-disease (HHD)." (PMID 31771413, 2019). "Mutations in ATP2C1 (SPCA1) manifest as Hailey-Hailey disease, an autosomal dominant skin disorder." (PMID 29925776, 2018).
Hailey-Hailey disease (continued). "In support of this is that siRNA knockdown of the calcium transporter ATP2C1 gene, mutated in the inherited skin blistering disease Hailey-Hailey disease, causes an increase in the expression of Claudins 1 and 4, and loss of cell-surface expression of tight junction proteins." (PMID 23685254, 2013). "Hailey-Hailey disease, an autosomal dominant disorder characterized by suprabasal acantholysis, is a cornification disorder associated with mutations in the ATPase secretory pathway Ca2+ transporting 1 (ATP2C1) gene encoding intracellular calcium pumps resulting in abnormal cytosolic Ca+2 levels." (PMID 32806619, 2020). "The Pmr1 protein can be replaced by its human homolog SPCA1 encoded by the ATP2C1 gene and mutations affecting calcium and/or manganese transport activities of SPCA1 are linked to Hailey-Hailey disease (HHD,)." (PMID 36555348, 2022). "Whole genome sequencing of the affected dog was performed, and the functional candidate genes for Darier disease (ATP2A2) and Hailey-Hailey disease (ATP2C1) were investigated." (PMID 32354065, 2020). "Hailey-Hailey disease is an autosomal genetic disease caused by mutations in one of the two ATP2C1 alleles encoding the secretory pathway Ca2+/Mn2+-ATPase, hSPCA1." (PMID 31455819, 2019). "We have developed a model yeast system to study the poorly defined genetic functions of the ATP2C1 gene in Hailey-Hailey disease development." (PMID 29925776, 2018). "ATP2C1-nonsyndromic epidermal differentiation disorder, also known as familial benign chronic pemphigus or Hailey-Hailey disease, is a rare autosomal dominant acantholytic disorder characterized by relapsing and remitting painful vesicles and erosions in flexural areas." (PMID 42222696, 2026). "Notably, SPCA1 is encoded by the ATP2C1 gene, which is mutated in benign chronic pemphigus (also known as Hailey-Hailey disease)." (PMID 36134951, 2022). "Hailey-Hailey disease (HHD; also known as familial benign pemphigus) is a human autosomal-dominant skin disease caused by the loss of one functional copy of the ATP2C1 gene, characterized by acantholysis (a disruption of cell-cell contacts) in the suprabasal layers of the skin." (PMID 23344038, 2013). "The loss of one ATP2C1 allele causes Hailey-Hailey disease in humans but not mice." (PMID 23344038, 2013).
lung cancer (20 papers, 2014 to 2025). A malignant neoplasm involving the lung. "ATP2C1 depletion abrogated Mn-induced GOLIM4 degradation in 3q-amplified cells, and ectopic coexpression of GOLIM4 and ATP2C1 sensitized a 3q-diploid lung cancer cell line (H23) to Mn treatment." (PMID 38662435, 2024). "Moreover, ATP2C1 depletion phenocopied the effect of GOLIM4 depletion in 3q-amplified lung cancer cells." (PMID 38662435, 2024). "Located on the 3q amplicon, ATP2C1 is coamplified with GOLIM4, and ATP2C1 mRNA levels are correlated with ATP2C1 gene copy numbers and GOLIM4 mRNA levels in TCGA lung cancer cohorts." (PMID 38662435, 2024). "In reconstitution studies carried out on GOLIM4-deficient cells, a short form of GOLIM4 that lacked the alternatively spliced exon (GOLIM4-ΔE7) did not bind to ATP2C1 or rescue secretory, tumorigenic, or metastatic activities of GOLIM4-deficient lung cancer cells." (PMID 38662435, 2024).
Darier disease (3 papers, 2017 to 2024). Darier disease (DD) is a keratinization disorder characterized by the development of keratotic papules in seborrheic areas and specific nail anomalies. "ATP2A2 is associated with Darier's disease (OMIM #124200), whereas pathogenic variants of ATP2C1 cause Hailey–Hailey disease (OMIM #169600)." (PMID 38804677, 2024).
pemphigus (3 papers, 2022 to 2023). Pemphigus is a group of rare autoimmune diseases that cause blistering of the skin and mucous membranes (mouth, nose, throat, eyes, and genitals).This conditioncan occur at any age, but often strikes people in middle or older age. "More recently, autoantibodies against Dsc1 and Dsc3, mitochondrial proteins, human leukocyte antigens, molecules, thyroid peroxidase (TPO), a Ca2+/Mn2+-ATPase encoded by ATP2C1 (hSPCA1), and several muscarinic and nicotinic AChRs have been identified as novel targets for pemphigus autoimmunity." (PMID 36979046, 2023).
prostate carcinoma (2 papers, 2022 to 2025). A carcinoma that arises from epithelial cells of the prostate gland. "Moreover, circATP2C1 expression in prostate cancer cells did not change significantly after RNase R treatment, whereas mRNA expressions of linear ATP2C1 and GAPDH were significantly reduced." (PMID 41228362, 2025).
colorectal cancer (1 paper, 2013). A primary or metastatic malignant neoplasm that affects the colon or rectum. "The ATP2C1/ASTE1 partial overlap (arrowheads) could represent a human-specific regulatory mechanism; when ASTE1 is mutated (e.g., in human colorectal cancers) the SPCA1 protein could accumulate, potentially leading to secretory pathway abnormalities and eventually neoplastic transformation." (PMID 23344038, 2013). "When ASTE1 is down-regulated or mutated (e.g., in 80% of colorectal cancers), it no longer prevents the formation of the ATP2C1 isoforms-b, c and d, which are less sensitive to miRNA-mediated inhibition." (PMID 23344038, 2013).
Condyloma Acuminatum (1 paper, 2021). "We report a 24-year-old male, who was presented with condyloma acuminatum-like lesions and a novel splice-site mutation in the ATP2C1 gene from a Chinese family with HHD." (PMID 34970303, 2021).
melanoma (1 paper, 2022). A malignant, usually aggressive tumor composed of atypical, neoplastic melanocytes. "Nevertheless, mTORC1 hyperactivation is known to promote tumor progression, and carcinoma and melanoma formation have previously been associated with mutations in the human PMR1 ortholog ATP2C1 that cause Hailey-Hailey disease." (PMID 35904415, 2022).
viral infections (1 paper, 2020). "The DC subsets shared an anti-apoptotic profile and the down-regulation of ATP2C1, a gene previously shown to correlate with resistance and decreasing viral spread in other viral infections (paramyxovirus, togavirus, flavivirus)." (PMID 33365028, 2020).
tumor (18 papers, 2013 to 2025). "We identified a region of chromosome 3q that is amplified in diverse tumor types and encodes multiple regulators of secretory vesicle biogenesis, including the Golgi scaffold Golgi integral membrane protein 4 (GOLIM4) and its client protein ATPase secretory pathway Ca2+ transporting 1 (ATP2C1)." (PMID 38662435, 2024). "They found that miR-519 inhibits the growth and survival of tumor cells via repressing the expression of proteins involved in DNA maintenance (including DUT1, EXO1, RPA2, and POLE4) and intracellular calcium homeostasis (ATP2C1 and ORAI1)." (PMID 37601663, 2023).
cancer (10 papers, 2013 to 2024). A tumor composed of atypical neoplastic, often pleomorphic cells that invade other tissues. "In this issue of the JCI, Tan and colleagues describe functional cooperativity between the Golgi-resident proteins Golgi integral membrane protein 4 (GOLIM4) and ATPase secretory pathway Ca2+ transporting 1 (ATP2C1) in the coordination of a secretory program in 3q-amplified cancers." (PMID 40047887, 2024). "Mutations in one allele of human ATP2C1, and thus low levels of the SPCA1 protein, cause a decrease in protein trafficking efficiency—enough for survival, but degenerating into HHD and rarely into cancer." (PMID 23344038, 2013).
genodermatosis (3 papers, 2013 to 2025). "Background/Objectives: Hailey–Hailey disease (HHD) is an uncommon genodermatosis with autosomal dominant inheritance caused by loss-of-function mutations in the ATP2C1 gene, which lead to disruption in keratinocyte adhesion and intraepidermal acantholysis." (PMID 40136584, 2025). "This genodermatosis is due to mutations in the ATP2C1 gene, which encodes the adenosine triphosphatase enzyme." (PMID 39411604, 2024).
skin disorder (3 papers, 2016 to 2023). Any deviation from the normal structure or function of the skin or subcutaneous tissue that is manifested by a characteristic set of symptoms and signs. "The genetics and pathophysiology of this skin disorder have been linked to mutations in the ATP2C1 gene." (PMID 29925776, 2018). "Mutations on the human ATP2C1 gene, causing decreased levels of the SPCA1 expression, have been identified as the cause of the Hailey–Hailey disease, a rare skin disorder." (PMID 27277681, 2016). "Pathogenic variants in ATP2C1 are causative for autosomal dominant Hailey‐Hailey disease (OMIM # 169600), a blistering skin disorder." (PMID 36910591, 2023). "Moreover, we plan to follow the probands with ATP2C1 and ATP2A2 variants to see if interventions targeting their skin disorders will also ameliorate their IC/BPS symptoms." (PMID 36910591, 2023).
heart disease (2 papers, 2023 to 2024). "However, dysfunction of the Golgi apparatus not specifically coupled to ATP2C1 has been associated with heart disease." (PMID 39241028, 2024).
autosomal dominant disease (1 paper, 2015). Autosomal dominant form of disease. "Genetically, HHD is an autosomal dominant disease, resulting from heterozygous mutations in ATP2C1, which encodes a Ca2+/Mn2+ATPase." (PMID 25658765, 2015).
ATP2C1 also shares sentences with these, for which no sentence is quoted: breast carcinoma (10 papers); lung adenocarcinoma (8); Familial benign chronic pemphigus (3); genetic disease (2); infection (2); ischemic stroke (2); Autoimmunity (1); bone metastasis (1); breast (1); Brody myopathy (1); Cerebral ischemia (1); cervical cancer (1); colon adenocarcinoma (1); colon cancers (1); cornification disorder (1); coronary artery disease (1); diabetes (1); gastric cancer (1); heart failure (1); manganese poisoning (1); neuroblastoma (1); non-small cell lung carcinoma (1); small cell lung carcinoma (1); squamous cell tumors (1).